IL17A (interleukin 17A)
Diseases named in the same sentence as IL17A in open-access papers (continued):
Sharing a sentence is not in itself a finding about the gene and the disease.
atherosclerosis (continued). "The impact of IL-17A on atherosclerosis can be attributed to the inflammatory microenvironment, including Treg cells and cytokines, which determine whether it promotes plaque instability or stability." (PMID 39104857, 2024). "Within its biological effects, IL-17A might promote accelerated atherosclerosis, which is a key extra-articular manifestation of RA." (PMID 37035302, 2023). "It has been proposed that IL17A contributes to atherogenesis by inducing vascular and systemic inflammatory responses, and inhibition of IL17A with αIL17A antibodies ameliorates experimental atherosclerosis." (PMID 35282365, 2022). "A large number of studies have shown that IL-17A is up-regulated in atherosclerosis, and its pathophysiological role in promoting atherosclerosis may be to increase plaque size and aggravate inflammation." (PMID 35371044, 2022). "Interleukin (IL)-17A has been shown to accelerate atherosclerosis." (PMID 35282365, 2022). "Th17 cells and Yδ T cells are the main producers of IL17A in atherosclerosis in ApoE−/− mice." (PMID 35282365, 2022). "Moreover, IL-17A was involved in accelerating atherosclerosis via enhancing FABP4-mediated endoplasmic reticulum (ER) stress in macrophages." (PMID 36311201, 2022). "Meanwhile, IL-17A inhibition produced regression of atherosclerosis with lower expression of the chemokines, proinflammatory cytokines, and adhesion molecules, suggesting a modulatory role of IL-17A in vascular inflammation and related atherosclerosis." (PMID 34836245, 2021). "In the context of atherosclerosis, IL-17A is the most well-studied member of this cytokine family." (PMID 33562334, 2021). "The blockade of IL-17A in mice resulted in a significant reduction in atherosclerosis." (PMID 35087531, 2021). "Indeed, IL-17A, and moreover when combined with TNFα, induces endothelial dysfunction, vascular inflammation and atherosclerosis and finally promotes occurrence of CVE." (PMID 32983142, 2020). "Therefore, the roles of Th17 cells and IL-17A in atherosclerosis is still an obscure area for intensive study." (PMID 32849502, 2020). "Due to its pleiotropic character, IL-17A is involved in the development of atherosclerosis, hypertension, fibrosis, diabetic nephropathy, ischemia-reperfusion injury, glomerulonephritis, nephrotic syndrome, minimal change disease, and acute renal allograft rejection." (PMID 32961903, 2020). "In this regard, IL-17A signaling has been extensively studied in preclinical atherosclerosis." (PMID 31572188, 2019). "IL-17A also plays a role in the development of kidney diseases, including glomerulonephritis, nephrotic syndrome, diabetic nephropathy, and acute renal allograft rejection, as well as in atherosclerosis and hypertension." (PMID 31719568, 2019). "Other research demonstrated that IL-17A mediates inflammation and the inappropriate increased vascular superoxide (O2-) production in response to high-fat diet-induced atherosclerosis, one of the crucial determinants of endothelial dysfunction in the setting of vascular disease." (PMID 32010143, 2019). "Highly expression levels of IFN-γ and IL-17A are shown in the animal model of atherosclerosis, while IL-10 and TGF-β1 have been proven to act as key anti-inflammatory agents in vivo and content elevation of IL-10 and TGF-β1 effectively attenuate the expansion of atheroma plaques." (PMID 31379468, 2019). "Role of Th17 and its signature cytokine, IL-17A, in atherosclerosis is controversial." (PMID 30069429, 2018). "This hypothesis is further supported by a murine model of atherosclerosis; inhibition of IL-17A led to prevention of lesion progression and induction of plaque stabilization in advanced lesions." (PMID 30109481, 2018). "By contrast, deciphering the exact role of IL-17A in atherosclerosis remains a challenging task." (PMID 29675020, 2018).
atherosclerosis (continued). "Mast cell infiltration and IL-17A expression are also observed in spondyloarthritis synovial inflammation, and both mast cells and neutrophils (as opposed to T cells) are major cellular sources of IL-17 in atherosclerosis." (PMID 30109481, 2018). "IL-17A is a pleiotropic cytokine with effects on multiple cell types to enhance the production of proinflammatory molecules and several lines of evidence have shown it is involved in the pathogenesis of atherosclerosis." (PMID 25615631, 2015). "Indeed, neutralizing IL-17 by IL-17A specific antibodies or administration of soluble IL-17 receptors reduces inflammation in animal models of atherosclerosis." (PMID 25352848, 2014). "A decrease in NO related to IL-17A may lead to endothelial dysfunction that can result in atherosclerosis and an increase in CIMT, as reported by Madhur and Nguyen." (PMID 25273526, 2014). "IL-17A and its roles during atherosclerosis are controversial." (PMID 23859810, 2013). "Notably, IL-17A that was thought to play a pro-atherogenic role in atherosclerosis was down-regulated, however, the relevance of IL-17A to human atherosclerosis remains poorly defined." (PMID 24349031, 2013). "Therefore, the aim of this study was to establish whether IL-17A gene promoter methylation is associated with the incidence of different stages of CAD, i.e., subclinical atherosclerosis and CAD with clinical manifestations." (PMID 38132456, 2023). "Therefore, the exact role of IL-17A in the progression of atherosclerosis is still controversial." (PMID 35371044, 2022). "In addition to IL-17A and IL-17F, IL-17C and IL-17E can also aggravate psoriatic lesions; meanwhile, IL-17A and IL-17C can enhance atherosclerotic plaque instability, and IL-17E is protective against atherosclerosis." (PMID 35514987, 2022). "Here, the inflammatory molecules in our panel that showed the most significance in PD, and particularly IL-1α, IL-1β, IL-17A, and TNF-α are all known to be dysregulated in cardiovascular disease and their presence in circulation might be linked to atherosclerosis." (PMID 31507404, 2019). "We speculated that IL-17A might promote the migration of vascular smooth muscle cells from the vascular media to the intima, resulting in intimal thickening, which is similar to their role in atherosclerosis." (PMID 25551434, 2014). "IL-17A is known to play a role in autoimmune and inflammatory diseases, including rheumatoid arthritis, psoriasis, multiple sclerosis, asthma, and inflammatory bowel disease, and in chronic vascular inflammation, atherosclerosis, and hypertensive vascular changes." (PMID 25273526, 2014). "Thus, the role of IL-17A in atherosclerosis remained controversial." (PMID 22808218, 2012). "This study suggests a link between elevated levels of IL-17A and TNF-α and subclinical atherosclerosis." (PMID 39104857, 2024). "This study aimed to measure the associations between different inflammatory factors, namely interleukin (IL)-17A, tumor necrosis factor (TNF)-α, and high-sensitivity C-reactive protein (hs-CRP), and atherosclerosis in patients with psoriasis vulgaris." (PMID 39104857, 2024). "Affibody molecule neutralizing IL17A, or sham were administered in vitro to human aortic smooth muscle cells (HAoSMCs) and murine NIH/3T3 fibroblasts and in vivo to atherosclerosis-prone, hyperlipidaemic ApoE−/− mice." (PMID 35282365, 2022). "Supporting a role for IL-17A in ECM production, the inhibition of IL-17A in atherosclerosis with neutralizing antibodies has been shown to prevent fibrous cap formation by reducing collagen accumulation." (PMID 35626694, 2022). "We focus on the contribution of cytokine networks encompassing IL-4, IL-6, IL-9, IL-17A, IL-33 but also IFN-γ and TNF-α to vascular dysfunction in atherosclerosis." (PMID 32194407, 2020).
atherosclerosis (continued). "Hematopoietic ablation of Il27ra accelerated atherosclerosis due to enhanced activation of CD4+ T cells, in particular, Th17 cells, accompanied by increased IL-17A, TNF-α and IL-6 production, CCL2 chemokine expression and accumulation of myeloid cells." (PMID 28536468, 2017). "IL-17C and TNF-β, elevated in AD, have overlapping signaling pathways with IL-17A/F and TNF-α, which are thought to contribute to atherosclerosis in psoriasis." (PMID 28821884, 2017). "Our data are supported by other reports that IL-17A is induced by the NAD(P)H-oxidase dependent generation of ROS, leading to a pro-inflammatory activation in atherosclerosis." (PMID 27389701, 2016). "A number of other pathways were identified (P <0.001) including IL17a, DC and NK crosstalk, LPS/IL-1 mediated inhibition of RXR function, leukocyte extravasation signaling, atherosclerosis signaling, and aryl hydrocarbon receptor signaling." (PMID 26503507, 2015). "Similarly, miR-151-3p, downregulated by ox-LDL, targets interleukin-17A (IL-17A) and inhibits the apoptosis of ECs induced by ox-LDL in atherosclerosis." (PMID 40076710, 2025). "The median IL-17A serum level in healthy controls was significantly lower than in psoriasis vulgaris patients with atherosclerosis (p < 0.05) but not in those without atherosclerosis (p > 0.05)." (PMID 39104857, 2024). "The median (IQR) of IL-17A in psoriasis vulgaris patients without and with atherosclerosis was 1.19 (0.43–2.66) and 1.30 (0.43–4.28) pg/mL, respectively (p < 0.05)." (PMID 39104857, 2024). "Clinical periodontal parameters, TNF-α and IL-8 in GCF and IL-17A, hs-CRP, and LDL in serum, had more significant predictive roles in developing subclinical atherosclerosis (IMT ≥ 0.75 mm) in comparison with other cytokines, fibrinogen, and other lipid status parameters." (PMID 36983201, 2023). "Additionally, IL-17A synergistically interacts with other inflammatory cytokines, and the overall dysregulation of these mediators may participate in host alterations that lead to oral dysbiosis and play a pivotal role in the pathogenesis of DM, atherosclerosis, RA, and adverse pregnancy outcomes." (PMID 37623290, 2023). "Besides, we and others have reported that IL-17A was elevated in patients with acute coronary syndrome (ACS) and atherosclerosis animal models." (PMID 22808218, 2012). "Furthermore, given the distinct plasticity of Th17 cells across various inflammatory contexts, the role of IL‐17A in atherosclerosis is not unequivocal." (PMID 41143276, 2025). "The detection of IL-17A-producing CD4+ T-cells in the atherosclerotic plaques of mice supports the possibility that subsets of Th17 cells may be recruited into the vascular beds and locally fuel atherosclerosis." (PMID 38247848, 2024). "Moreover, IL-17A stimulated oxidized low-density lipoprotein (oxLDL)-induced foam cell formation by upregulating LOX-1 in activated macrophages, thereby participating in atherosclerosis pathogenesis." (PMID 36211578, 2022). "Neutralization of IL-17A not only reduced the atherosclerotic plaques but also down regulated IL-6, TNF-α and CCL5 that suggests that regulation of these cytokines may be interconnected in atherosclerosis." (PMID 23437105, 2013). "Hence, comparable to the pathogenesis of atherosclerosis and RA, inflammatory mediators, including TNF-α, IL-1β, IL-6, and IL-17A, generated in the context of periodontitis can enter the systemic circulation and trigger an acute-phase response that could negatively impact the placenta and fetus." (PMID 37623290, 2023). "Previous studies suggested that TNF-α, and other inflammatory cytokines such as IL-17A, may has a role in inducing the formation of neutrophil extracellular traps (NETs), which is a specific type of cell death involved in many diseases including both VET and atherosclerosis." (PMID 33519488, 2020).
atherosclerosis (continued). "Psoriasis vulgaris patients with atherosclerosis had higher levels of hs-CRP (median = 1.22; interquartile range—IQR = 0.34–12.11) and IL-17A (median = 1.30; IQR = 0.43–4.28), but a lower level of TNF-α (median = 0.54; IQR = 0.13–3.41) compared to those without atherosclerosis (p < 0.05)." (PMID 39104857, 2024).
Autoimmunity (543 papers, 2007 to 2026). The occurrence of an immune reaction against the organism's own cells or tissues. "This interaction triggers signaling pathways that promote the production of inflammatory cytokines associated with autoimmunity, such as IL-17A and IFN-γ." (PMID 40722611, 2025). "IL-17A, produced by Th17 cells, is increased in CNP rat models, and the upregulation of IL-17A is associated with autoimmunity and inflammatory response." (PMID 41573743, 2025). "This miRNA cluster is connected to the pathogenicity of Th17 due to pathogenic cytokine production, including IL-17A and IL-17F, and mediates autoimmunity by repression of FOXO1 and induction of IL-1R1 expression." (PMID 37834058, 2023). "IL-17A promotes the production of corresponding myeloid cells by recruiting pathogenic T cells and plays an initiating role in autoimmunity." (PMID 37370521, 2023). "The up- or down-regulation of IL-17 genes (IL-17A, IL-17B, IL-17D, and IL-17F) resulted in decreased expression of many cytokines and chemokines, which are associated with autoimmunity and immune cell functions." (PMID 35466218, 2022). "IL-17A plays many roles in immunoregulation and has been associated with chronic inflammatory diseases and autoimmunity." (PMID 35404942, 2022). "In support, IL-17A has been directly implicated in critical steps of autoimmunity comprising the emergence and stabilization of autoreactive GC formation, AICDA upregulation, class switching to IgG2a and IgG3, and autoantibody generation." (PMID 35620115, 2022). "Th17 cells and the secreted proinflammatory mediator IL-17A can cause autoimmunity and an inflammatory response." (PMID 33743834, 2021). "Both 17F and IL-17A cytokines have been implicated in allergic inflammation and inflammation resulting from mucosal immunity or autoimmunity." (PMID 33571165, 2021). "IL-17RA is the receptor for IL-17A, a cytokine associated with autoimmunity and implicated in rodent models of ASD." (PMID 30483058, 2018). "Our studies also found that nPA suppressed in vitro mouse splenocyte production not only of IFN-γ but also of other autoimmunity-associated cytokines such as interleukin-17A, whose production also requires NF-κB activation." (PMID 29935534, 2018). "CCR6, the gene encoding chemokine (C-C motif) receptor 6, a surface marker for Th17 cells at 6q27, is critically involved in IL-17A-driven autoimmunity in diseases and associated with RA susceptibility." (PMID 27822475, 2016). "The cells were first identified by their ability to produce interleukin 17A (IL-17A) and, subsequently, associated with chronic inflammation and autoimmunity." (PMID 26101460, 2015). "In Th17 cytokine families, IL-17A is identified as the key cytokine associated with autoimmunity, inflammation and host defence." (PMID 25551434, 2014). "Mounting evidence suggests that IL-17A causes pathology in autoimmunity, but little is known about mechanisms of IL-17RA signaling." (PMID 19400960, 2009). "IL-17A is a pro-inflammatory mediator that is prominently associated with autoimmunity." (PMID 38638687, 2024). "Moreover, RAC1, along with TIAM1, is implicated in interleukin 17A (IL-17A) transcription and has a role in autoimmunity." (PMID 38577601, 2024). "IL-17A also controls the gut microbiota, and its disruption causes autoimmunity." (PMID 37588589, 2023). "In this regard, IL-17A has been directly implicated in critical steps of autoimmunity." (PMID 35620115, 2022). "IL17A is an important factor that leads to the induction of autoimmunity-causing IBD." (PMID 33929018, 2021). "IL-17a is known to be implicated in autoimmunity and the pathogenesis of IBD." (PMID 29720595, 2018). "Although the prototype Th17 cell cytokines, IL-17A/F, have been strongly linked to autoimmunity in multiple animal models, there has been recent evidence that a fraction of Th17 cells also co-express IFN-γ at the site of inflammation with reported functional consequences." (PMID 28736556, 2017).
Autoimmunity (continued). "Prior research has established that microbiota-derived SCFAs modulate the Th17/Treg imbalance in autoimmune pathologies by attenuating IL-17A production." (PMID 41481427, 2026). "Our preliminary data indicated that EBV DNA elevates the systemic levels of the pro-inflammatory cytokine IL-17A, a marker that is highly correlated with autoimmunity." (PMID 40722611, 2025). "In a study, the anti-interleukin-17A (anti-IL-17A) aptamer effectively blocked the biological effects of IL-17A and suppressed the development of autoimmunity in mouse joint inflammation models." (PMID 40487355, 2025). "IL‐17A has previously been implicated in neurological autoimmunity, including in LGI1‐AE, with CSF IL‐17A levels previously shown to correlate with disease severity in the acute phase." (PMID 40781580, 2025). "IL-17A-expressing lymphocytes, including Tc17 cells, are instrumental in immunity, immunopathology, and autoimmunity." (PMID 40453072, 2025). "In turn, Th17-derived IL-17A potently stimulates neutrophil activation and NETosis, creating a self-amplifying loop that exacerbates autoimmunity." (PMID 41376642, 2025). "In turn, Th17-derived IL-17A potently stimulates neutrophil activation and NETosis, creating a self-amplifying, positive-feedback loop that exacerbates autoimmunity and chronic inflammation." (PMID 41376642, 2025). "Simultaneously, IL-17A can stimulate the production of cytokines via the IL-17A receptor pathway, resulting in autoimmunity and tissue damage." (PMID 40218314, 2025). "IL-17A plays an important role in regulating host autoimmunity, various inflammatory diseases, and tumor immunity." (PMID 38494504, 2024). "For the brain, IL-17A has been shown to induce glial cell activation and is involved in the initiation and development of CNS diseases, such as autoimmunity, autism, and stroke." (PMID 38067176, 2023). "It is widely recognized that IL17A is essential for the onset and progression of autoimmune conditions." (PMID 37189748, 2023). "Th17 cell is one lineage of T helper cells originated from naive CD4+ T cells, and secretes pro-inflammation cytokines, such as IL-17A and IL-17F, participating in inflammatory response, autoimmunity, and transplant rejection." (PMID 36792629, 2023). "Taken together, CNS-targeted expression of IL-17A facilitated induction of T-cell-mediated autoimmunity in the CNS." (PMID 36857006, 2023). "In this study, we were able to demonstrate that CNS-specific IL-17A synthesis facilitates the induction of CNS autoimmunity and permits spontaneous infiltration of autoreactive T-cells into the CNS." (PMID 36857006, 2023). "Innate immune cells, particularly those related to the γδT cell portion, participate in IL17A generation at the initial stage of autoimmune disorders." (PMID 37189748, 2023). "IL-17A, which is produced mainly by Th17 cells, mediates autoimmunity and immune defense against pathogens, and is increased in the intestinal mucosa of patients affected by chronic inflammatory bowel disorders, such as celiac disease, CD, and UC." (PMID 36833379, 2023). "Herein, the discussion is focused on IL-17A, IL-17C and IL-17F, since these families mediate autoimmunity the best, albeit in the presence of other additional families." (PMID 35203707, 2022). "IL-17A performs a key task in host defense against fungal and bacterial infections, as well as in the development of autoimmunity, inflammation, and tumors." (PMID 35480154, 2022). "Owing to the key role of IL-17A in the pathophysiology of chronic inflammation and autoimmunity, therapeutic strategies targeting the pro-inflammatory cytokine were inevitably developed." (PMID 35159158, 2022). "This is critical for the maturation and development of IL17A‐producing T cells, with its imbalance downstream potentially resulting in autoimmunity." (PMID 35092700, 2022). "IL-17A is involved in inflammation and autoimmunity, while IL-17F is predominantly involved in mucosal defense mechanisms." (PMID 36396672, 2022).